LONP2 (lon peptidase 2, peroxisomal)
Description:
ATP-dependent serine protease that mediates the selective degradation of misfolded and unassembled polypeptides in the peroxisomal matrix. Necessary for type 2 peroxisome targeting signal (PTS2)-containing protein processing and facilitates peroxisome matrix protein import (By similarity). May indirectly regulate peroxisomal fatty acid beta-oxidation through degradation of the self-processed forms of TYSND1.
Synonyms: pLon; LONP; MGC4840; LONPL; PSLON
Tractability: PROTAC: ubiquitination databases record sites on it; its protein half-life has been measured.
Gene: Protein-coding gene on chromosome 16 (48,244,267 to 48,363,122, forward strand). Ensembl gene ENSG00000102910.
Subcellular location: Peroxisome matrix
Pathways (Reactome):
Metabolism of proteins: Association of TriC/CCT with target proteins during biosynthesis
Protein localization: Peroxisomal protein import
Gene Ontology:
Molecular function: enzyme binding; peptidase activity; protease binding; protein binding; ATP binding; ATP hydrolysis activity; ATP-dependent peptidase activity; serine-type endopeptidase activity
Biological process: protein processing; protein targeting to peroxisome; regulation of fatty acid beta-oxidation; peroxisome organization; protein catabolic process; protein import into peroxisome matrix; protein quality control for misfolded or incompletely synthesized proteins; proteolysis
Cellular component: membrane; peroxisomal matrix; peroxisome; cytosol; cytoplasm; nucleus
Genetic constraint (gnomAD): Loss-of-function variants: 53 observed, 73.52 expected, observed/expected ratio (o/e) 0.72, 90% interval 0.58 to 0.91. The upper end of that interval is the gene's LOEUF score, 0.91, which puts it in group 3 of 6, group 1 being the genes least tolerant of losing a copy. Missense variants: 786 observed, 997.19 expected, observed/expected ratio (o/e) 0.79, 90% interval 0.74 to 0.84. Synonymous variants: 373 observed, 365.47 expected, observed/expected ratio (o/e) 1.02, 90% interval 0.94 to 1.11.
Homologues: Orthologues: chimpanzee LONP2 (99% identical), dog LONP2 (97% identical), pig LONP2 (96% identical), macaque LONP2 (96% identical), mouse Lonp2 (96% identical), rabbit LONP2 (96% identical), rat Lonp2 (95% identical), guinea pig LONP2 (94% identical), tropical clawed frog lonp2 (84% identical), zebrafish lonp2 (78% identical), Caenorhabditis elegans lonp-2 (35% identical). Paralogues in human: LONP1 (35% identical).
Diseases named in the same sentence as LONP2 in open-access papers:
LONP2 is named in the same sentence as 11 diseases in open-access papers, as found by Europe PMC text mining. Sharing a sentence is not in itself a finding about the gene and the disease. The quoted sentences say what the papers report.
breast carcinoma (1 paper, 2022). "This could explain why the knockdown of certain proteases, such as Lonp2, Clpx and Clpp, only affects breast cancer growth under normoxic culture conditions strong enough to be detected as a screen deletion hit." (PMID 36313646, 2022).
cervical cancer (1 paper, 2018). A primary or metastatic malignant neoplasm involving the cervix. "A down-regulation of LonP2 in the tumor cell lines HeLa and SiHA reduced oxidative stress and inhibited cervical cancer cell proliferation and migration." (PMID 30219925, 2018). "As the study, however, lacks any further analysis on the peroxisomal status in the cervical cancer cells or LonP2 depleted cell lines, it is currently impossible to mechanistically explain how the changes in LonP2 expression might modify peroxisome physiology with respect to cancerogenesis." (PMID 30219925, 2018).
lung squamous cell carcinoma (1 paper, 2023). "TMEM120B, HMOX2, CALCOCO2, LONP2, ZNF440, CLCC1, and CHMP3 were identified to be optimal prognostic factors for lung squamous cell carcinoma (LUSC)." (PMID 36999050, 2023).
cancer (2 papers, 2022 to 2026). A tumor composed of atypical neoplastic, often pleomorphic cells that invade other tissues. "LONP2 encodes for a peroxisome enzyme responsible for selectively degrading oxidatively damaged proteins, and is found to be upregulated in various cancers, in particular cervical cancer." (PMID 41513643, 2026).
tumor (1 paper, 2022). "Interestingly, significantly negative correlations between chr12:122215052A > I level and TMEM120B expression, chr19:11945758A > I level and ZNF440 expression, chr1:109474650A > I level and CLCC1 expression, chr16:48388244A > I level and LONP2 expression, were observed in LUSC tumor tissues." (PMID 35768804, 2022).
LONP2 also shares sentences with these, for which no sentence is quoted: dilated cardiomyopathy (1 paper); glioma (1); heart failure (1); leukemia (1); lung carcinoma (1); metabolic disorders (1).